NLRP3 (NLR family pyrin domain containing 3)
Diseases named in the same sentence as NLRP3 in open-access papers (continued):
Sharing a sentence is not in itself a finding about the gene and the disease.
cardiac arrest (continued). "Of course, we cannot eliminate that the activation of NLRP3 inflammasome exists in the liver or kidney after cardiac arrest at the molecular level, and pharmacologic blockage of NLRP3 inflammasome may exert a protective effect on these tissues." (PMID 32703306, 2020). "Without such information, the potential of NLRP3 inflammasome inhibition and autophagy induction as therapeutic approaches for ischemic injury associated with cardiac arrest and worsened by comorbid stress will likely remain elusive." (PMID 32466385, 2020). "We then explored whether the suppression of microglia pyroptosis and consequential inflammatory response improved outcomes by targeting NLRP3 with MCC950 in cardiac arrest modeling rats." (PMID 32703306, 2020). "Moreover, the delivery of MCC950 led to a significant reduction in the number of CD45high CD11b+ cells accompanied by the inhibition of IL-1β and IL-18, suggesting that the intervention of NLRP3 by MCC950 prevents the post-cardiac arrest inflammatory response." (PMID 32703306, 2020). "Consistently, the protein level of NLRP3 was elevated at 6 to 24 h after cardiac arrest." (PMID 32703306, 2020). "Therefore, we tested the activation of NLRP3 inflammasome after cardiac arrest, aiming to provide potential targets for mediating microglial pyroptosis." (PMID 32703306, 2020). "Therefore, for the first time, we show that the NLRP3 inflammasome-mediated microglial pyroptosis is crucially involved in the development of neuroinflammation after cardiac arrest." (PMID 32703306, 2020). "Taken together, these results suggest that MCC950 significantly prevents histological injuries, which might be via interfering NLRP3 inflammasome activation and suppressing microglia pyroptosis in the brain after cardiac arrest." (PMID 32703306, 2020). "In this study, we provide evidence for the activation of TLR2 and TLR4 in immediate survivors of cardiac arrest and describe the involvement of the NLRP3 inflammasome in the modulation of the subsequent systemic inflammatory response to global IRI caused by temporary circulatory arrest." (PMID 27260481, 2016). "The presence of IL-18 and IL-1β led us to hypothesize the presence and activation of the NLRP3 inflammasome in response to localized tissue injury and cardiac arrest." (PMID 26635801, 2015). "However, after cardiac arrest and cardiopulmonary resuscitation, whether the assembly of NLRP3 inflammasome primes microglia and mediates its pyroptosis and consequential neuroinflammation remains unclear." (PMID 32703306, 2020). "In addition, whether blocking NLRP3 inflammasome is beneficial for alleviating the post-cardiac arrest brain injury remains to be further explored, although it has been shown that blocking the inflammasome is beneficial in cerebral ischemic diseases like stroke in the previous studies." (PMID 32703306, 2020). "As shown by the co-immunoprecipitation, pairwise interactions among NLRP3, ASC, and caspase-1 were observed in both the hippocampus and cortex tissues at 12 h after cardiac arrest." (PMID 32703306, 2020). "Here, we revealed that NLRP3 and ASC were upregulated in the post-cardiac arrest brain with biological interaction, and both NLRP3 and ASC had interaction with caspase-1, which represent the intracellular activation of NLRP3 inflammasome." (PMID 32703306, 2020). "The results from qRT-PCR and Western blotting showed that MCC950 significantly suppressed the levels of NLRP3, ASC, IL-1β, and IL-18 at 12 h after cardiac arrest, in both hippocampus and cortex." (PMID 32703306, 2020). "In analysis of time-dependent expression of monocyte mRNA in patients after cardiac arrest, significantly higher levels of TLR2, TLR4, IRAK3, NLRP3, and IL1B were observed in patients in the early hours after ROSC compared to the later phase." (PMID 27260481, 2016). "Monocyte TLR2, TLR4, IRAK3, IRAK4, NLRP3, PYCARD and IL1B were initially upregulated in patients following cardiac arrest." (PMID 27260481, 2016).
cardiac arrest (continued). "Nonsurvivors at 30 days had significantly lower mRNA levels of TLR2, IRAK3, IRAK4, NLRP3 and CASP1 in the late phase following cardiac arrest." (PMID 27260481, 2016). "Therefore, our findings provide evidence that targeting NLRP3 by MCC950 suppresses the occurrence of microglial pyroptosis and consequential inflammatory response after cardiac arrest." (PMID 32703306, 2020). "The mode of injury (cardiac arrest and CPR versus severe traumatic injury) may explain our findings of lower NLRP3 mRNA levels in TP after admission." (PMID 29861655, 2018).
eosinophilia (9 papers, 2017 to 2024). "By contrast, the autoinflammatory disease CAPS, caused by NLRP3 mutations, is associated with peripheral eosinophilia and eosinophilic skin infiltration." (PMID 35281022, 2022). "In contrast, infecting NLRP3-deficient mice with helminths augmented early innate immune cell recruitment, eosinophilia, and neutrophilia, as well as type-2 cytokine responses, while the presence of NLRP3 attenuated immunopathological changes in the tissue environment." (PMID 33673676, 2021). "On the other hand, infected WT control mice presented evident peritoneal eosinophilia and surprisingly, this population was found to be significantly reduced in WT animals co-housed with resistant NLRP3−/− mice." (PMID 38842647, 2024). "Eosinophilia correlates with CAPS disease activity, suggesting that NLRP3 activation promotes eosinophilia." (PMID 35281022, 2022). "The data thus far demonstrated that Nlrp3−/− mice displayed elevated neutrophilia and eosinophilia in the lung and protective immunity in the early stages of primary infection, accompanied by an enhanced type 2 effector response in the intestine." (PMID 31586037, 2019). "Unexpectedly, compared with wild-type (WT) mice, infected Nlrp3−/− mice had increased neutrophilia and eosinophilia, correlating with enhanced worm killing but at the expense of increased tissue damage and delayed lung repair." (PMID 31586037, 2019). "This correlated with enhanced Ccl24 (Eotaxin-2) expression and increased eosinophilia in infected Nlrp3−/− mice." (PMID 31586037, 2019). "However, Nlrp3−/− mice exhibited enhanced features of type 2 immunity, including lung eosinophilia and increased intestinal goblets cells." (PMID 31586037, 2019). "In order to avoid diagnostic delay and its dire consequences, NLRP3-AID should be suspected in patients displaying autoinflammatory features combined with serum and tissue eosinophilia and/or marked serositis, regardless of skin involvement." (PMID 36510304, 2022). "In the hippocampus the reduced eosinophilia and the almost complete absence of shrunken neurons encourages the hypothesis that NLRP3 inflammasome absence might be protective for the relatively long-term sequelae of TBI." (PMID 28769794, 2017).
frontotemporal dementia (9 papers, 2018 to 2026). Frontotemporal dementia (FTD) comprises a group of neurodegenerative disorders, characterized by progressive changes in behavior, executive dysfunction and language impairment, as a result of degeneration of the medial prefrontal and frontoinsular cortices. "We therefore conducted a comprehensive assessment of the effects of chronic trazodone treatment on microglial activation, the NLRP3 inflammasome, the UPR, EEG sleep, and memory in rTg4510 mice, a model expressing the human P301L tau mutation linked to hereditary frontotemporal dementia." (PMID 35273086, 2022). "Moreover, it has been reported that the microglial activation of the NLRP3 inflammasome drives tau pathology in a mouse model of frontotemporal dementia, shedding a light on the role of microglia in the development of AD." (PMID 33066071, 2020). "Interestingly, mice expressing human tau mutations as well as patients affected by primary tauopathies, such as frontotemporal dementia, exhibited increased NLRP3 levels." (PMID 33066071, 2020). "Activation of NLRP3 inflammasome (as reflected by the increased level of cleaved caspase-1) and ASC speck-like aggregates were found in the hippocampus of patients with frontotemporal dementia (FTD) as well as in a mouse model of tau pathology (Tau22 mice which expressed human tau mutation for FTD)." (PMID 35693341, 2022).
glomerular diseases (9 papers, 2019 to 2025). "According to this data kidney injury in PE occurs not only due to TI, but also glomerulopathy which could be a result of coagulopathy and/or hemolysis associated with NLRP3 activity, and these processes are described in following sections of this article." (PMID 32650532, 2020). "Specifically, NLRP3 activation drives glomerular disease through pyroptosis, leading to mesangial expansion and glomerular thickening." (PMID 35755447, 2022). "One of several mechanisms through which NLRP3 drives glomerular disease is through increased pyroptosis, a form of programmed cell death stimulated by inflammation." (PMID 35755447, 2022). "NLRP3 inflammasome was activated in tubulointerstitial and glomerular diseases, promoting proinflammatory cytokines IL-1β and IL-18 production and excretion, causing renal inflammatory injuries." (PMID 32116724, 2020). "Another study in glomerular disease also suggested the elevated mRNA levels of NLRP3 and CASPASE-1 gene with respect to normal individuals." (PMID 31551961, 2019). "Thus, in addition to the NLRP3-inflammasome playing an important role in podocyte injury in glomerular diseases, we believe this is the first report of its role in podocyte senescence and aging." (PMID 37487005, 2023). "In addition to autophagy regulation in CKD, NLRP3 inflammasome activation has been characterized to mediate diverse aspect mechanisms of urate nephropathy through regulation of proinflammatory cytokines, tubulointerstitial injury, glomerular diseases, renal inflammation, and fibrosis pathways." (PMID 32582712, 2020). "NLRP3 inflammasome activation has been characterized to mediate diverse aspect mechanisms of CKD through regulation of proinflammatory cytokines, tubulointerstitial injury, glomerular diseases, renal inflammation, and fibrosis pathways." (PMID 32582712, 2020).
gram-negative bacterial infections (9 papers, 2017 to 2026). Infections caused by bacteria that show up as pink (negative) when treated by the gram-staining method. "Thus, the mechanisms underlying NLRP3 inflammasome, mTOR activity, and phagosome/lysosome in defense of Gram-negative bacterial infection still require clarification." (PMID 33117816, 2020). "MS-based proteomics in independent retinal and cortical cohorts reveal a dysregulated Chlamydia interactome enriched for gram-negative bacterial infection, NLRP3 inflammasome components, pyroptosis executors, and cell-death pathways." (PMID 41571675, 2026). "Cp infection, among other gram-negative bacterial infections, activates the NLRP3 inflammasome via LPS, driving inflammatory cascades and cellular degeneration." (PMID 40667156, 2025). "Caspase-11-dependent NLRP3 inflammasome activation was also reported during gram-negative bacterial infection." (PMID 29311802, 2017). "Our proteomic analyses further supported our histological findings and identified dysregulated pathways associated with the immune response to intracellular obligatory, gram-negative bacterial infection, TLR and NLRP3 inflammasome activation, and cell death in both the retina and brain." (PMID 40667156, 2025). "Type I IFN is necessary for IL-1β production by the non-canonical NLRP3 inflammasome in response to Gram-negative bacterial infection." (PMID 32373120, 2020). "In the non-canonical NLRP3 inflammasome pathway, IL-1β induction in mice and humans after Gram-negative bacterial infections required interferon (IFN)-inducible caspase-11 in mice, or caspase-4/5 in humans." (PMID 32373120, 2020). "Unlike the canonical pathway, caspase-4 has been shown to act as the major caspase involved in non-canonical NLRP3 inflammasome activation and it has been demonstrated that Gram-negative bacterial infections induce the non-canonical pathway, which results in cellular damage and death via pyroptosis." (PMID 38177104, 2024).
hepatitis C (9 papers, 2013 to 2025). "In conclusion, this study reports, for the first time, the association of genetic variations in NLRP3 with hepatitis C susceptibility and response to treatment in Egyptian patients." (PMID 30728751, 2019). "In conclusion, the present study reported, for the first time, that the genetic polymorphisms in NLRP3 (rs1539019 and rs35829419) are associated with hepatitis C susceptibility and response to treatment in Egyptian patients." (PMID 30728751, 2019). "Similarly, heterozygote carriers for CTSB rs1692816 and AIM2 rs1103577 (padj = 0.008) or for IL18 rs187238 and NLRP3 rs10754558 (padj = 0.005), have less chances to the development of hepatitis C." (PMID 34161370, 2021). "In the present study, we analyzed whether polymorphisms in inflammasomes genes IL1B rs16944, IL18 rs187238, NLRP3 rs10754558, CARD8 rs2009373, CTSB rs1692816 and AIM2 rs1103577 are associated with susceptibility to HCV infection and liver fibrosis in hepatitis C patients in the Amazon population." (PMID 34161370, 2021). "In hepatitis C-infected livers, the activation of SREBP and NLRP3 is mutually observed, and in the liver of STZ-induced diabetic rats, suppression of TNXIP causes concurrent downregulation of SREBP and NLRP3 activity." (PMID 39139641, 2024). "In one study among patients with Hepatitis C (sustained virological responders against non-responders groups), the NLRP3 rs10754558 had no influence on treatment." (PMID 34161370, 2021).
keratitis (9 papers, 2013 to 2023). A corneal disease that is characterized by inflammation of the cornea. "In human corneal epithelial cells or mice keratitis models, P. aeruginosa upregulated the inflammasome as well as pyroptosis-associated genes and activated the NLRP3/caspase-1/IL-1β pathway." (PMID 35655803, 2022). "The aim of this study was to determine whether NOD-like receptor family pyrin domain containing 3 (NLRP3) inflammasome-mediated pyroptosis contributes to Candida albicans (C. albicans) keratitis and explore the underlying mechanism." (PMID 35463001, 2022). "Genetic and pharmacologic approaches using MCC950 reveal that NLRP3 is also essential for bacterial killing and disease severity in a murine model of P. aeruginosa corneal infection (keratitis)." (PMID 37730693, 2023). "Currently, several studies have demonstrated that the NLRP3 inflammasome is involved in the pathogenesis of keratitis due to infection with A. fumigatus or Fusarium." (PMID 35463001, 2022). "In human corneal epithelial cells and mice models of A. fumigatus keratitis, pannexin 1 channels contributed to IL-1β expressions via NLRP3/caspase-1 inflammasome." (PMID 35655803, 2022). "In summary, our data demonstrated for the first time that NLRP3 inflammation-mediated pyroptosis plays an important role in mediating the immune response during C. albicans keratitis." (PMID 35463001, 2022). "Our results indicated that multiple proteins that were associated with inflammasome and pyroptosis (NLRP3, ASC, CAP1, GSDMD, IL-1β and IL-18) were highly expressed in C. albicans keratitis." (PMID 35463001, 2022). "Additionly, NLRP3 inflammasome-mediated pyroptosis during C. albicans keratitis is closely related to the inflammatory injury of cornea." (PMID 35463001, 2022). "Particularly, recent report indicated that neutrophil is the predominant cell in murine model of keratitis regarding NLRP3/ASC inflammasome and caspase-1 activation, and subsequent IL-1β processing." (PMID 31270454, 2019). "Although several reports in the cornea demonstrated the broad caspase-1 expression in neutrophils, macrophages, and corneal resident cells, neutrophils seem to be the predominant cell of caspase-1 expression in infectious keratitis model using NLRP3 KO mice." (PMID 31270454, 2019). "To determine whether NLRP3 inflammasome activation and pyroptosis are involved in C. albicans keratitis, we first verified NLRP3 expression in C. albicans-infected corneas." (PMID 35463001, 2022). "Abnormal activation of the NLRP3 inflammasome might contribute to intestinal cancer, inflammatory diseases, and autoinflammatory diseases such as keratitis/conjunctivitis." (PMID 32148650, 2020). "Using the NLRP3 inhibitor MCC950, Nlrp3-/- mice, and Nlrc4-/- mice, we also demonstrate that NLRP3 rather than NLRC4 is required for bacterial killing and preventing corneal perforation in P. aeruginosa keratitis." (PMID 37730693, 2023). "Therefore, the goal of this study was to explore whether NLRP3 inflammasome activation and pyroptosis are present in C. albicans-infected mouse corneas and human corneal epithelial cells (HCECs) and contribute to the pathogenesis of C. albicans keratitis and the potential mechanism." (PMID 35463001, 2022). "When the NLRP3 inflammasome is activated, a large amount of the proinflammatory cytokines IL-1β and IL-18 are released through GSDMD pores, which may trigger and aggravate corneal inflammation and result in enhanced ocular injury in C. albicans keratitis." (PMID 35463001, 2022). "However, we showed that in a murine model of P. aeruginosa keratitis, neutrophils mediate IL-1β secretion using serine proteases rather than caspase-1, although NLRP3 and ASC are reportedly expressed by neutrophils." (PMID 23750216, 2013).
nasopharyngeal carcinoma (9 papers, 2012 to 2025). A carcinoma arising from the nasopharyngeal epithelium. "In nasopharyngeal carcinoma triggered by EBV infection, EBV-encoded latent membrane protein 1 directly interacted with the glycolytic protein Glut1 to induce NLRP3 and IL-1β expression in myeloid-derived suppressor cells." (PMID 40041420, 2025). "This promotes the induction of GM-CSF, IL-6, and IL-1β production through COX-2 and NLRP3 inflammasome signaling pathways to enhance MDSCs differentiation and expansion, thereby promoting nasopharyngeal carcinoma (NPC) progression." (PMID 31275326, 2019). "In addition, NLRP3 can be used as an important prognostic marker for nasopharyngeal carcinoma patients." (PMID 35712482, 2022). "Here we show that the NLRP3, AIM2 and RIG-I inflammasomes are overexpressed in Epstein-Barr virus (EBV)-associated nasopharyngeal carcinoma (NPC), and expression levels correlate with patient survival." (PMID 23065753, 2012). "Compared with normal tissues, components of NLRP3 and AIM2 inflammasomes were highly expressed in nasopharyngeal carcinoma tissues, which correlated with an increased chance of survival in nasopharyngeal carcinoma." (PMID 35847844, 2022). "Another study examined the role of three proteins, Nod-like receptor protein 3 (NLRP3), cysteine-aspartic acid protease 1 (Caspase-1), and Gasdermin D (GSDMD), in nasopharyngeal carcinoma (NPC)." (PMID 39744516, 2025).